PRKACB (protein kinase cAMP-activated catalytic subunit beta)
Diseases named in the same sentence as PRKACB in open-access papers (continued):
Sharing a sentence is not in itself a finding about the gene and the disease.
gastric cancer (3 papers, 2025 to 2026). A primary or metastatic malignant neoplasm involving the stomach. "Whole genome-scale integrated analyses of exon arrays demonstrated that PRKACB is a novel cancer-related variant transcript in gastric cancers." (PMID 40302936, 2025). "It was reported that PRKACB expression was elevated in gastric cancer tissues and was associated with tumor development." (PMID 40255562, 2025). "GLI1 protein levels were significantly higher in gastric cancer tissues than in tumor-adjacent tissue samples, consistent with PRKACB protein levels in gastric cancer tissues." (PMID 40255562, 2025). "GLI1 and PRKACB expression was examined using immunohistochemistry in tissue microarrays containing 30 gastric cancer and 30 tumor-adjacent tissue samples." (PMID 40255562, 2025). "PRKACB has two isoforms, Cβ1 and Cβ2, of which the Cβ1 isoform is abnormally expressed in gastric cancer tissues." (PMID 40255562, 2025). "Our study showed that PRKACB is highly expressed in gastric cancer and acts as a downstream regulator of GLI1 to promote gastric cancer progression." (PMID 40255562, 2025). "Targeting GLI1 G4 structures with alpha-estradiol and (R)-(-)-ibuprofen effectively inhibits gastric cancer progression by blocking GLI1/PRKACB signaling." (PMID 40255562, 2025). "Our results have showed that G-quadruplex regulators on the GLI1 promoter inhibited gastric cancer progression by downregulating PRKACB, an effector molecule downstream of GLI1." (PMID 40255562, 2025). "To verify whether there was an association between GLI1 and PRKACB, we analyzed the data using the TIMER database and found that the correlation coefficient between PRKACB and GLI1 expression in gastric cancer was the highest amongst the analyzed tumors." (PMID 40255562, 2025). "In addition, G-quadruplex regulators of the GLI1 promoter inhibited gastric cancer cell proliferation, migration, and invasion by downregulating PRKACB, which provides more options for the clinical treatment of gastric cancer." (PMID 40255562, 2025). "Furthermore, we confirmed that G-quadruplex regulators of the GLI1 promoter inhibited gastric cancer progression by downregulating PRKACB, an effector molecule downstream of GLI1." (PMID 40255562, 2025). "Furthermore, this effect was confirmed by inhibition of the GLI/PRKACB pathway in gastric cancer." (PMID 40255562, 2025). "PRKACB expression was analyzed by immunohistochemistry in tissue samples from DGC and intestinal-type gastric cancer (IGC) patients." (PMID 41851075, 2026). "Therefore, PRKACB has an important physiological function; however, in gastric cancer, the function of PRKACB is not clear, and its upstream and downstream regulatory molecular pathways are rarely reported." (PMID 40255562, 2025).
lung carcinoma (3 papers, 2013 to 2020). "Increased PRKACB expression is possibly an effective inhibitor of lung cancer." (PMID 23833645, 2013). "Exogenously expressed PRKACB may effectively inhibit the progression of lung cancer." (PMID 23833645, 2013). "PRKACB is downregulated in non-small cell lung cancer (NSCLC), exogenous PRKACB inhibits the proliferation and invasion of lung cancer cells." (PMID 33201835, 2020). "However, there are no studies investigating the role of PRKACB in lung cancer." (PMID 23833645, 2013).
Papillary Thyroid Cancer (3 papers, 2020 to 2024). "Increased PRKACB levels in papillary thyroid cancer cells and adenoma of the pituitary gland suggest that PRKACB influences offspring growth during development through effects on the endocrine glands." (PMID 39342354, 2024). "ERBB3/ERBB4/RAF1 kinases were activated in papillary carcinoma compared to other variants, PAK3/PAK6/CDK1 kinases were activated in NOS, and PRKACA/PRKACB/PRKACG kinases were activated in differentiation variants." (PMID 35659036, 2022).
pituitary adenoma (3 papers, 2023 to 2026). "Potential associations include variants in emerging pituitary adenoma predisposition genes, including NF1, PRKACB, PAM, and CHEK2." (PMID 41965096, 2026).
prostate carcinoma (3 papers, 2013 to 2024). A carcinoma that arises from epithelial cells of the prostate gland. "It has been demonstrated that PRKACB variants play various roles in the differentiation and proliferation of prostate cancer." (PMID 33201835, 2020). "Multiple PRKACB subunits have also been observed in human prostate specimens and it appears that the PRKACB variants play varying roles in proliferation and differentiation of prostate cancer progression." (PMID 23833645, 2013). "In human prostate cancer cells, 5α-diol stimulated the accumulation of intracellular cAMP and reduced PRKACB expression." (PMID 39342354, 2024). "PRKACB tissue-specific expression has also been found in human brain, neuronal, lymphoid and prostate cancer tissues, and has been reported to be correlated with cellular proliferative or differentiation processes." (PMID 23833645, 2013).
Sepsis (3 papers, 2022 to 2026). Sepsis is defined as life-threatening organ dysfunction caused by a dysregulated host response to infection. "PRKACB, consistently decreased in sepsis, emerged as a myeloid-associated hub gene with functional support in macrophages." (PMID 41624837, 2026). "Pathway enrichment indicated distinct PRKACB-related functions between sepsis and healthy controls, and across myeloid subtypes." (PMID 41624837, 2026). "In the meantime, the expression of PRKAR1A and PRKACB, which are negative regulators for MAPK pathway, was also decreased in the sepsis cohort, while the expression of the other 5 genes was not significantly altered." (PMID 35187084, 2022).
Carney complex (2 papers, 2018 to 2022). Carney complex (CNC) is characterized by spotty skin pigmentation, endocrine overactivity and myxomas. "However, rare Carney Complex mutations are found in the catalytic Cα or Cβ subunits (encoded by PRKACA or PRKACB, respectively)." (PMID 36313756, 2022).
cognitive deficits (2 papers, 2019 to 2024). "However, variants of genes that are enriched or specifically expressed in brain tissues, such as PRKACB or PRKAR1B, appear to produce more cognitive deficits, as is the case with MASNS." (PMID 38481146, 2024).
ischemic stroke (2 papers, 2022 to 2024). A stroke disorder caused by obstruction of blood flow to the brain, due to thrombotic (local blood clot formation) or embolic (due to a blood clot or other material traveling from another site) event. "Interestingly, APAF1 and IRAK3 expression correlated negatively with NK cell abundance in both acute myocardial infarction and ischemic stroke, whereas ATM, CAPN1, IL1B, IL1R1, PRKACA, PRKACB, and TNFRSF1A correlated negatively with NK cell abundance in acute myocardial infarction." (PMID 35432334, 2022). "Interestingly, in acute MI and ischemic stroke, the expression of APAF1 and IRAK3 was negatively correlated with the abundance of NK cells, while the expression of ATM, CAPN1, IL1B, IL1R1, PRKACA, PRKACB and TNFRSF1A was positively correlated with the abundance of NK cells in MI." (PMID 38526027, 2024).
myxoma (2 papers, 2022 to 2023). A benign soft tissue neoplasm characterized by the presence of spindle and stellate cells, lobulated growth pattern, and myxoid stroma formation. "In addition, a single patient with CNC that presented with abnormal skin pigmentation, acromegaly and myxomas, was found to harbor copy number gains of locus containing the PRKACB gene." (PMID 36105398, 2022). "In addition, copy number gains involving the PRKACB locus (which encodes the Cβ catalytic subunit), were reported in a patient with CNC that presented with myxomas, acromegaly, and abnormal skin pigmentation." (PMID 36105398, 2022).
osteosarcoma (2 papers, 2021 to 2022). A usually aggressive malignant bone-forming mesenchymal neoplasm, predominantly affecting adolescents and young adults. "The four osteosarcoma cell lines generally exhibited higher TCEA3 expression and lower PRKACB, AIM1, and EVI2B compared with the osteoblast cell line (hFOB1.19)." (PMID 36275664, 2022).
type 2 diabetes (2 papers, 2020 to 2021). "In this context, it can be considered if hsa-miR-933 can also regulate MAP4K4 or other protein kinases (PRKCE, PRKACB) to control type II diabetes mellitus." (PMID 32993798, 2020). "The target genes that were significantly enriched for the development of type II diabetes mellitus in both modules are GNAS, PRKACB, PRKCE, MAP4K4, PEA15, and BDNF." (PMID 32993798, 2020). "From this information, it can be considered for the analysis if hsa-miR-933 can regulate the overexpressed PEA15, downregulated BDNF, or other ATF2 target genes (PRKACB, GNAS, PRKCE, and MAP4K4) to control type II diabetes mellitus." (PMID 32993798, 2020). "Our approach delineated that hsa-miR-933 might control the hyperglycemic condition and hyperinsulinism by regulating ATF2 target genes MAP4K4, PRKCE, PEA15, BDNF, PRKACB, and GNAS which can otherwise lead to the development of type II diabetes mellitus." (PMID 32993798, 2020).
benign ovarian tumour (1 paper, 2024). "We identified a de novo missense variant in PRKACB on ES re-analysis in an individual with ID, refractory focal epilepsy, spasticity, periventricular nodular heterotopia, a common atrium / AVSD, polydactyly and several tumours (benign ovarian tumour, liver haemangioma and renal cell carcinoma)." (PMID 39095811, 2024).
cecal adenocarcinoma (1 paper, 2020). "Besides, the PRKACB was also downregulated in cecal carcinoma (P<0.0005) and cecal adenocarcinoma (P<0.0001)." (PMID 32626531, 2020).
cocaine addiction (1 paper, 2022). "The differences between sexes in the expression of cocaine addiction genes such as CREB1 and protein kinases such as PRKACB have been previously reported in mice under other experimental conditions." (PMID 35627199, 2022).
colon carcinoma (1 paper, 2020). "Similarly, we were able to regulate the development of colon cancer by targeting PRKACB, providing an important theoretical basis for the development of colon cancer chemotherapeutic drugs and new anti-EMT therapies." (PMID 32626531, 2020).
COVID-19 (1 paper, 2023). A disease caused by infection with severe acute respiratory syndrome coronavirus 2. "The results indicated six hub DEGs for comparison of T1DM and COVID-19 convalescence (CD3G, YES1, ALAS2, MYO1C, NCR3, PRKACB) and two hub DEGs for comparison of T2DM and COVID-19 convalescence (PTRF, EHD1)." (PMID 38169604, 2023).
deafness (1 paper, 2021). An inherited or acquired condition characterized by the complete loss of the ability to hear from one or both ears. "It is thus reasonable to expect that a regulator of cochlear development, such as PRKACB, would be associated with congenial pediatric deafness." (PMID 34912812, 2021).
depression (1 paper, 2011). "PRKACB has been linked to depression as lower expression of PRKACB in the prefrontal cortex occurs in major depression." (PMID 22087873, 2011).
endocrine cancers (1 paper, 2020). "PRKACB gene has been identified to be an important oncogene in cancer progression, especially in the progression of endocrine cancers by modulating cAMP signaling activity." (PMID 31998791, 2020).
endocrine neoplasia (1 paper, 2024). "Nothing is known about the imprinting status of PRKACB in eutherian mammals although mutations of this gene are associated with endocrine neoplasia and other developmental disorders." (PMID 39342354, 2024).
glioma (1 paper, 2020). A benign or malignant brain and spinal cord tumor that arises from glial cells (astrocytes, oligodendrocytes, ependymal cells). "For case 10, the WGS indicated two candidate models that exhibited two or three copies of the whole chromosome 1 with focal amplification including the PRKACB gene, whose amplification in pediatric high-grade glioma has been reported previously." (PMID 32019606, 2020).
lung adenocarcinoma (1 paper, 2025). A carcinoma that arises from the lung and is characterized by the presence of malignant glandular epithelial cells. "PRKACB expression correlated with clinical parameters in lung adenocarcinoma specimens." (PMID 40255562, 2025).
mantle cell lymphoma (1 paper, 2013). Mantle cell lymphoma is a rare form of malignant non-Hodgkin lymphoma affecting B lymphocytes in the lymph nodes in a region called the ``mantle zone''. "PRKACB was identified as a candidate gene that is directly or indirectly involved in apoptosis in human mantle cell lymphoma (MCL) tumors." (PMID 23833645, 2013).
mucinous adenocarcinoma (1 paper, 2020). An invasive adenocarcinoma composed of malignant glandular cells which contain intracytoplasmic mucin. "Furthermore, in males (P = 0.0083), whites (P = 0.0463), and non-mucinous adenocarcinoma patients (P = 0.0108), the down-regulation of PRKACB expression was more significant for the OS prognostic value." (PMID 32626531, 2020).
neuroblastoma (1 paper, 2025). Neuroblastoma (NB) is the most common solid, extracranial childhood tumor. "Finally, both the mRNA and protein expression verification assays demonstrated that the CDKN3 and PCLAF were upregulated, while the PRKACB was downregulated in advanced-stage neuroblastoma tissue samples." (PMID 40302936, 2025). "The model containing CNR1, PRKACB, CDKN3, and PCLAF can serve as a new prognostic biomarker for predicting the prognosis of patients with neuroblastoma." (PMID 40302936, 2025). "CNR1, PRKACB, CDKN3, and PCLAF were found to significantly affect the overall survival and event-free survival of neuroblastoma patients and were positively correlated with the INSS advanced stages." (PMID 40302936, 2025). "Four prognostic genes (CNR1, PRKACB, CDKN3, and PCLAF) were identified, and a prognostic model based on these genes was developed that provides novel insights into the prognostic evaluation of neuroblastoma." (PMID 40302936, 2025).
ovarian carcinoma (1 paper, 2017). A malignant neoplasm originating from the surface ovarian epithelium. "PRKACB may involve in type 1 cAMP-dependent protein kinase a-related pathway which modulates breast, pancreatic, colon and ovarian cancers to be resistant to different cytotoxic agents." (PMID 28749961, 2017).
rectal carcinoma (1 paper, 2020). A malignant epithelial neoplasm that arises from the rectum and invades through the muscularis mucosa into the submucosa. "Notwithstanding, the difference of PRKACB expression in rectal carcinoma has no value (P = 0.2021)." (PMID 32626531, 2020).
cancer (26 papers, 2014 to 2026). A tumor composed of atypical neoplastic, often pleomorphic cells that invade other tissues. "The overexpression of CDK1, TYMS, CDT1, and CCNA2 and the underexpression of PRKACB were associated with tumorigenesis, defective cell signaling, or aberrant metabolism in other cancers." (PMID 31205467, 2019). "Dysregulation of protein kinase A catalytic subunit beta (PRKACB) has been implicated in various cancers, but its role in DGC remains unclear." (PMID 41851075, 2026). "Both GLI1and PRKACB have been reported to significantly promote the proliferation, migration, and invasion of cancer cells." (PMID 40255562, 2025). "GLI1 and PRKACB are highly correlated with cell stemness, so we further explored the correlation with cancer cell stemness." (PMID 40255562, 2025). "Mechanistically, GLI1 directly regulated PRKACB expression, and G4 stabilization downregulated PRKACB, impairing epithelial-mesenchymal transition and cancer stemness." (PMID 40255562, 2025). "In general, PRKACB activity has been positively correlated with the proliferation and growth of cancer cells." (PMID 39342354, 2024). "We analyzed them via ‘EXPANSION’, including a set of sixteen reported PRKACB isoforms, nine of which show significant differential expression in cancer tissues." (PMID 37810457, 2023). "Over these past years, more and more data indicate that PRKACB is involved in the cancerization process of malignant tumors in different systems." (PMID 32626531, 2020). "It has been reported that GST, EGFR and PRKACB are responsible for signal transduction pathways involved in tumor growth and differentiation in different type of cancers." (PMID 25928635, 2015). "The findings suggested that NSCLC tissues showed much lower levels of both PRKACB mRNA and protein than the corresponding normal tissues and in transfected cancer cell lines, PRKACB upregulation reduced the number of proliferative, clonogenic, and invasive cells, while apoptosis rates was increased." (PMID 38987822, 2024). "Metascape database analysis revealed that the target mRNAs PRKACB and PDCD4 of miR-550a-3p as well as RPS6KA5 and BCL2L2 of miR-550a-5p were associated with miRNA cancer pathway, providing important clues for subsequent studies on the mechanism underlying EAC development." (PMID 36829221, 2023). "PRKACB stabilizes elF4F expressed at high level in different carcinomas." (PMID 24597747, 2014). "Moreover, PRKACB might be a promising target in cancer treatment by increasing drugs responsiveness to tumors." (PMID 31285693, 2019). "A total of 20 target mRNAs of three miRNAs were predicted, among which seven target mRNAs—ASAP3, BCL2L2, LMF1, PPM1L, PTPN21, SLC18A2, and NR3C2—had prognostic value; PRKACB, PDCD4, RPS6KA5, and BCL2L2 were enriched in the miRNA cancer pathway." (PMID 36829221, 2023). "More biological investigation should be conducted in future to validate the correlation of three potential miR-146a-5p targets (PRKACB, ADCY2, and ADCY5) and miR-146a-5p in cancers." (PMID 31285693, 2019).